NTRK2 (neurotrophic receptor tyrosine kinase 2)
Diseases named in the same sentence as NTRK2 in open-access papers (continued):
Sharing a sentence is not in itself a finding about the gene and the disease.
Alzheimer disease (81 papers, 2011 to 2026). A progressive, neurodegenerative disease characterized by loss of function and death of nerve cells in several areas of the brain leading to loss of cognitive function such as memory and language. "Some studies have identified significant associations of NTRK2 gene polymorphisms with responses to lithium drug treatment in patients with bipolar disorder, Alzheimer’s disease or cognitive performance in the elderly." (PMID 40869374, 2025). "NTRK2 polymorphisms have so far been studied for association with childhood-onset mood disorders, Alzheimer’s disease, suicidality and antidepressant response." (PMID 23750220, 2013). "We uncovered a significant enrichment for processes regulating amyloid-beta formation, revealing that hc-RAE expression impacts Alzheimer’s disease risk genes that include APOE, ABCA7, CLU, NTRK2, and more." (PMID 36640362, 2023). "Among the differentially expressed proteins, there were proteins involved either in the neurogenic process (e.g. GDF11) or in Alzheimer’s disease (e.g. LRRK2, RCAN1, NTRK2), or in both neurogenesis and Alzheimer’s disease (e.g. CREBBP, SFRP1, IL1RAP)." (PMID 36703180, 2023).
schizophrenia (78 papers, 2008 to 2025). A major psychotic disorder characterized by abnormalities in the perception or expression of reality. "A specific BDNF SNP (single nucleotide polymorphism) and other BDNF haplotypes, linkage peaks and NTRK2 (TrkB) gene variations are associated with autism, bipolar disorder, schizophrenia, OCD and ADHD." (PMID 29691724, 2018). "The aim of the present study is to investigate the role of BDNF functional Val66Met polymorphism (rs6265), three polymorphisms in NTRK2 gene (rs1387923, rs2769605 and rs1565445) and their interaction in pathophysiology of paranoid schizophrenia." (PMID 24069289, 2013). "NTRK2 together with BDNF is associated with paranoid schizophrenia." (PMID 30090857, 2017). "Thus, the possible role of other genes in the BDNF/NTRK2 signaling pathway and their interactions on susceptibility to schizophrenia should be further examined." (PMID 24069289, 2013). "However, we found the association between the interaction of BDNF and NTRK2 with paranoid schizophrenia by using the MDR method followed by conventional statistical analysis." (PMID 24069289, 2013). "Moreover, the interaction between BDNF and NTRK2 gene polymorphisms may increase susceptibility to paranoid schizophrenia." (PMID 34831151, 2021). "For example, the ATAAT haplotype (5 SNP NTRK2) is associated with a reduced risk of schizophrenia in men, and the GTAGCC haplotype [5 SNP NTRK2 and 1 rs6265-C (V64V) SNP of the BDNF gene] is associated with a reduced risk of it in women." (PMID 38646100, 2024). "Consistent with the findings presented here, previous studies reported changes in DNA methylation within the Gad1 and Ntrk2 gene promoters in rodent models of stress and humans suffering from schizophrenia, bipolar disorder, or depression." (PMID 30874581, 2019). "Previous studies have found a strong link between neurotrophic receptor tyrosine kinase 2 (NTRK2) and psychiatric disorders, such as schizophrenia." (PMID 31245181, 2019). "Recently, BDNF and its high-affinity receptor, NTRK2, widely expressed in the adult brain, were both reported decreased in human postmortem of schizophrenia suggesting they were involved in pathophysiology of schizophrenia." (PMID 24069289, 2013). "Altered NTRK2 expression has been identified in the brains of patients with schizophrenia." (PMID 29693535, 2018). "NTRK2, a susceptibility gene of paranoid schizophrenia, was not only overexpressed in paranoid schizophrenia, but also suppressed in undifferentiated and disorganized schizophrenia." (PMID 28809853, 2017). "In the present study, we recruited 402 patients with paranoid schizophrenia and 406 control subjects to examine the putative association between paranoid schizophrenia and polymorphisms in BDNF (rs6265) and NTRK2 genes (rs1387923, rs2769605, and rs1565445) in a Chinese Han population." (PMID 24069289, 2013). "However, no literature reported the association between those three NTRK2 gene polymorphisms and the susceptibility to schizophrenia." (PMID 24069289, 2013). "Genes with consistently lower expression levels in both medial rectus and schizophrenia tissues included NPY1R, TIMP2, and possibly NTRK2." (PMID 29302405, 2017). "Comparing baseline levels between muscle types, three schizophrenia-related genes (NPY1R, NTRK2, TIMP2) had lower levels of expression in medial rectus muscles." (PMID 29302405, 2017). "When gene expression by PCR arrays was analyzed exclusively in the medial rectus samples, we found that three schizophrenia-related genes were significantly altered: NPY1R, NRG1, and NTRK2 (adjusted p ≤ 0.012500)." (PMID 29302405, 2017). "Among proteins showing the highest enrichment in the mGlu2 interactome, we focused on BDNF/NT-3 growth factor receptor TrkB (also called NTRK2, highlighted in green), given the well-documented influence of the BDNF/TrkB axis on the pathophysiology of schizophrenia." (PMID 38277461, 2024).
schizophrenia (continued). "The data for inherent, absolute “baselines” of expression between medial and lateral rectus muscles revealed two genes with similar directionalities between EOMs and schizophrenia (NPYR1, NTRK2), while two others (TCF4, TIMP2) went in the opposite direction (slight increase in blood)." (PMID 29302405, 2017). "Neurotrophic tyrosine kinase receptor 2 (NTRK2) is the high-affinity receptor of BDNF, and was reported to be associated with mood disorders, though no literature reported the association with schizophrenia." (PMID 24069289, 2013). "However, up to date, no literature reported the correlation between NTRK2 gene (rs2769605, rs1387923, and rs1565445) and schizophrenia." (PMID 24069289, 2013).
glioma (68 papers, 2012 to 2025). A benign or malignant brain and spinal cord tumor that arises from glial cells (astrocytes, oligodendrocytes, ependymal cells). "Paediatric gliomas express high levels of the BDNF receptor TrkB (encoded by NTRK2) in malignant cells." (PMID 37914930, 2023). "Replicating this experiment using an orthogonal approach, we knocked down NTRK2 expression using short hairpin RNA (shRNA) rather than CRISPR-mediated deletion, demonstrating a similar reduction in synaptic puncta in TrkB-deficient glioma cells." (PMID 37914930, 2023). "Genetic expression patterns of the neurotrophin receptors in DMG tumours, suggests that BDNF acts on glioma cells through the TrkB (encoded by NTRK2) receptor and that BDNF is a key neurotrophin to which paediatric glioma cells respond." (PMID 37914930, 2023). "Together, these results demonstrate a previously unidentified role for the NTRK2 splice variant TrkB.T1 in gliomas and highlight the importance of exploring alternative splicing of TRKs in basic and translational research." (PMID 32532995, 2020). "In our cohort and the glioma TCGA cohort, low expression of NTRK2 and high expression of CHI3L1 were strongly linked to poor prognosis (p < 0.05)." (PMID 30991699, 2019). "We hypothesized that NTRK2 loss in glioma cells may alter the degree of malignant synaptic connectivity." (PMID 37914930, 2023). "Here, we show a role for a truncated NTRK2 splice variant, TrkB.T1, in human glioma." (PMID 32532995, 2020). "Our in-depth transcript level analyses suggest additional components of NTRK2 biology may be implicated in gliomas." (PMID 32532995, 2020). "Therefore, CHI3L1 associated with NTRK2 seemed to be able to provide new information on glioma prognosis." (PMID 30991699, 2019). "The beneficial effect of NTRK2 overexpression on OS confirms recent data reporting that loss of mRNA expression of both NTRK1 and NTRK2 correlates with poor prognosis in patients with high-grade glioma, but our analysis adds a location-specific link to the picture." (PMID 27782828, 2016). "Knockout of 5HT2A in glioma cells nearly abolished psilocybin-induced proliferation, whereas NTRK2 knockout partially attenuated this effect." (PMID 41427306, 2025). "We present a case of high-grade glioma in a 6-year-old patient with a rare TRIM24::NTRK2-fusion, having had five tumor relapses in 4 years." (PMID 41331048, 2025). "Molecular profiling revealed that 72% of gliomas harbored NTRK2 fusions, while NTRK1 and NTRK3 fusions were identified in 13% and 15% of cases, respectively." (PMID 40647390, 2025). "NTRK2 fusions were found in ten cerebral diffuse low-grade and high-grade gliomas (DLGGs and DHGGs, respectively), and NTRK1 fusions were found in one cerebral desmoplastic infantile ganglioglioma and one spinal DHGG." (PMID 39014476, 2024). "AMPAR trafficking to the glioma cell membrane is promoted by docking of BDNF to the receptor NTRK2, resulting in an increased amplitude of glutamate-evoked currents in the malignant cells." (PMID 38834748, 2024). "Alterations in CDK4/6, CIC, FGFR2/3/4, FUBP1, KIT, MET, NF1, PEG3, RB1, and NTRK2 were additional factors correlated with the survival of different subtypes of gliomas." (PMID 36998447, 2023). "We used CRISPR technology to delete NTRK2 from human, patient-derived glioma cells (referred to as NTRK2-knockout (KO))." (PMID 37914930, 2023). "Using immuno-electron microscopy with immunogold labelling of GFP+ cells to unambiguously identify the malignant cells, we identified fewer neuron-to-glioma synaptic structures in the NTRK2-KO tumours compared with wild-type tumours." (PMID 37914930, 2023). "We sought to investigate the relative contribution of BDNF–TrkB signalling in neuron–glioma interactions using neuronal co-culture with NTRK2 wild-type or NTRK2-KO glioma cells." (PMID 37914930, 2023).
glioma (continued). "We found that pharmacologically blocking AMPARs or genetically blocking TrkB through NTRK2 knockout decreased tumour cell proliferation in vivo or in neuron–glioma co-culture." (PMID 37914930, 2023). "The other NTRK2 fused glioma (KANK1:NTRK2), originally diagnosed as ependymoma, was classified as pleomorphic xanthoastrocytoma (PXA) (CS 0.90)." (PMID 36163281, 2022). "By contrast, NTRK2 fusions more exclusively exist in central nervous system (CNS) tumors like gliomas, according to a study where NTRK2 fusion was detected in most NTRK fusion-positive patients (9/14)." (PMID 35372074, 2022). "We found NTRK2-243aa was significantly decreased in glioma tissues and was negatively correlated with pathological grades." (PMID 36064939, 2022). "The 7 adult patients all had high-grade gliomas and ranged from 26 to 78 years old with all but one of the fusions involving NTRK2." (PMID 35673607, 2022). "CHI3L1 and NTRK2 were identified as factors that can be associated with IDH1 status and 1p/19q codeletion to distinguish between prognostic groups of glioma from the TCGA cohort." (PMID 34458259, 2021). "Given the little understanding in the function of NTRK2/3 fusions in glioma, we emphatically describe NTRK1 fusions here." (PMID 34671307, 2021). "An analysis has therefore been carried out using NGS (Next Generation Sequencing) technique on the glioma cells of our patient, showing the presence of fusion-transcripts of the NTRK2 gene." (PMID 33921960, 2021). "Of these significantly correlated genes, the top 350 genes for each tumor type were subjected to gene ontology (GO) analysis to determine which, if any, classes of genes were enriched in NTRK2 glioma pairings." (PMID 32532995, 2020). "CHI3L1 and NTRK2, whose expression is associated with 1p19q co-deletion and IDH status, refined the prognosis of glioma patients, but this should be confirmed by a prospective study." (PMID 30991699, 2019). "Combined molecular groups based on the presence or absence of the four tumor markers (IDH status, 1p19q co-deletion status and CHI3L1 and NTRK2 expression levels) were used to classify the 671 glioma cases in the TCGA cohort according to prognosis." (PMID 30991699, 2019). "Among these genes, CHI3L1 and NTRK2 were identified as factors that can be associated with IDH status and 1p/19q co-deletion to distinguish between prognostic groups of glioma from the TCGA cohort." (PMID 30991699, 2019). "NTRK2 is expressed in the majority of glioma cells at varying levels across the defined cellular subpopulations that comprise DMGs, including oligodendrocyte precursor cell-like tumour cells (OPC-like), astrocyte-like tumour cells (AC-like) and oligodendrocyte-like tumour cells (OC-like)." (PMID 37914930, 2023). "NTRK2 fusions generally occur in other types of cancer, especially in gliomas." (PMID 33923728, 2021). "Our NTRK2 transcript-level analysis of normal brain and human gliomas reveals relatively low amounts of full-length TrkB.FL compared with abundant amounts of TrkB.T1 in tumor tissue, suggesting that this isoform has an important role in both normal neurobiology and oncogenesis alike." (PMID 32532995, 2020). "In comparison, the majority of pediatric NTRK-fused gliomas involved NTRK2 (69.2%, 9/13)." (PMID 32665022, 2020). "We have also observed that the NTRK gene involved in the rearrangement differs in frequency by age, with pediatric gliomas having a high percentage of rearrangements involving NTRK2 (69.2%), and adult gliomas having a high percentage of rearrangements involving NTRK1 (68.2%)." (PMID 32665022, 2020). "For the first time, we propose that CHI3L1 and NTRK2 could act as new biomarkers to improve the assessment of glioma prognosis." (PMID 30991699, 2019).
glioma (continued). "In addition to endocytic and vesicular compartment GO terms, DGCA GO analysis for positive NTRK2 correlations in glioma reactome pathways revealed enrichment for genes in the PI3K and mTOR signaling pathways, which have been known to regulate cellular proliferation in normal and oncogenic contexts." (PMID 32532995, 2020). "Fusions of NTRK1, NTRK2, and NTRK3 genes belong to the genomic landscape of diverse types of gliomas." (PMID 39039193, 2024). "A variety of NTRK fusion types (NTRK1, NTRK2, and NTRK3) have also been described in pediatric high-grade gliomas." (PMID 39087020, 2024). "Co-culture of NTRK2-KO glioma cells exhibited fewer synaptic structures with neurons evident as co-localized neuronal presynaptic puncta (synapsin) with glioma postsynaptic puncta (PSD95–RFP), compared with NTRK2 wild-type glioma cells." (PMID 37914930, 2023). "NTRK2 signalling, mediated by the soluble brain-derived neurotrophic factor BDNF, plays a major role in cell survival promotion of growth in glial tumours." (PMID 35473984, 2022). "Fusions involving the neurotrophin receptor tyrosine kinase genes (NTRK1, NTRK2, and NTRK3) recur in cancers like gliomas, secretory breast cancer, and lung cancer." (PMID 35127532, 2021). "Most adult NTRK-fused gliomas involved NTRK1 (68.2%, 15/22), with NTRK3 (18.2%, 4/22) and NTRK2 (13.6%, 3/22) comprising subsets of cases." (PMID 32665022, 2020). "Expression of HERV-W env in human glioma cells results in a two- to fourfold increase in expression of brain-derived neurotrophic factor (BDNF), neurotrophic tyrosine kinase receptor type 2 (NTRK2), and dopamine receptor D3 (DRD3)." (PMID 26793126, 2015). "Confirming that glioma cell TrkB activation mediates the change in glutamate-evoked current amplitude, NTRK2 knockout prevented the BDNF-induced increase in glutamate-evoked inward current amplitude, compared with NTRK2 wild-type glioma xenografted cells." (PMID 37914930, 2023). "We observed that NTRK2-243aa was downregulated in GBM and negatively correlated with glioma grades." (PMID 36064939, 2022). "To investigate whether BDNF–TrkB signalling regulates the number of neuron-to-glioma synaptic connections, we performed immuno-electron microscopy in the brains of mice bearing wild-type and NTRK2-KO patient-derived glioma xenografts expressing GFP." (PMID 37914930, 2023). "In addition to glioma, this alteration has also been noted in a treatment-refractory pilocytic astrocytoma, though with fusion to exon 13 rather than 17 of the NTRK2 gene." (PMID 35673607, 2022). "The exceptions are three genes (NTRK2, EPHB3, and EPB41L2), which are known to play a role in neural systems, and only appear in some of the core modules from the two cancer types of neural origin, gliomas and melanoma, and NSCLC that expresses prominent features of neuroendocrine cells." (PMID 22691569, 2012). "To further test whether BDNF–TrkB signalling regulates the number of neuron-to-glioma synaptic connections, we co-cultured glioma cells—with or without NTRK2 expression and expressing RFP-tagged PSD95—with neurons and quantified neuron-to-glioma synaptic puncta." (PMID 37914930, 2023). "Last but certainly not least, fusion oncoproteins involving the TRKA, TRKB, and TRKC tyrosine kinases (which are encoded by NTRK1, NTRK2, and NTRK3, respectively) have been identified across nine tumor types, including sarcoma, melanoma, gliomas, thyroid, lung, colon, breast, head and neck cancers)." (PMID 29455648, 2018). "All mouse glioma models analyzed, regardless of strain, genetic background, or oncogenic driver showed strong diffuse staining for expression of endogenous TrkB.T1 within the tumor boundaries, suggesting that TrkB.T1 may be selected for as the predominant NTRK2 isoform across multiple tumor types." (PMID 32532995, 2020).
glioma (continued). "Although entrectinib decreased the proliferation rate of xenografted NTRK2 wild-type DIPG cells in vivo, it did not further decrease the proliferation rate of NTRK2-KO glioma xenografts, demonstrating that the mechanism of action of entrectinib in DIPG is mediated through TrkB." (PMID 37914930, 2023).
epilepsy (59 papers, 2013 to 2026). A brain disorder characterized by episodes of abnormally increased neuronal discharge resulting in transient episodes of sensory or motor neurological dysfunction, or psychic dysfunction. "The genetic associations of BDNF and NTRK2 with epilepsy have been studied, while their roles in epilepsy remain controversial and need to be verified." (PMID 33262686, 2020). "Here, we report a novel NTRK2 rearrangement in a 24-year-old female with dysembryoplastic neuroepithelial tumor (DNT), a circumscribed WHO grade I benign tumor associated with epilepsy." (PMID 36531047, 2022). "Our ongoing study will increase the sample size and validate the role of ADORA2A, BDNF, and NTRK2 in epilepsy." (PMID 33262686, 2020). "This underscore BSN, BDNF and NTRK2 interconnection in epilepsy, corroborated in this study." (PMID 24278214, 2013). "Comparison of ADORA2A rs2298383, BDNF rs6265, and NTRK2 rs1778929 diplotype distribution between childhood epilepsy (CE) patients with and without neurologic comorbidities." (PMID 33262686, 2020).